CD36 (CD36 molecule (CD36 blood group))
Diseases named in the same sentence as CD36 in open-access papers (continued):
Sharing a sentence is not in itself a finding about the gene and the disease.
cancer (continued). "In terms of cancer metastasis, dietary PA has been found to promote the metastasis of oral cancer and melanoma in mice, and this PA-induced prometastatic memory requires the involvement of the FATP CD36." (PMID 41421797, 2025). "We focused on ENPEP, TIMP1, CD36, MARCKS, DAB2, CXCL14, miR-181b-5p, and miR-222-3p—genes and miRNAs previously implicated in cancer but not comprehensively analyzed in the context of EVs in BC." (PMID 40565366, 2025). "CD36-mediated activation of SRC/MAPK, AKT/GSK3β/β-catenin signaling axes, STAT3, and SOX2 had been shown to induce epithelial-mesenchymal transition (EMT) and promote proliferation, cancer stemness, metastasis as well as drug resistance." (PMID 40709184, 2025). "Irradiation induces a dose-dependent increase in cancer cells expressing PS without affecting CD36 expression in THP-1 or MCF-7 cells." (PMID 39752516, 2025). "The uptake of extracellular lipids via CD36 and the lipolysis-stimulated lipoprotein receptor (LSR) is often upregulated in tumors and is also responsive to PI3K/mTOR signaling, reinforcing the lipid supply for cancer progression." (PMID 40901479, 2025). "In the case of metabolic abnormalities, CD36-mediated inhibition of AMPK activation may promote DNL and cancer cell proliferation." (PMID 40814339, 2025). "Furthermore, Immune subtype analysis showed that CD36 expression was high in C6 (TGF-beta Dominant) and C3 (Inflammatory) immune subtypes across various cancer types." (PMID 41550652, 2025). "Our findings support our hypothesis that CD36 and CD47 can be used as prognostic biomarkers for multiple cancer indications." (PMID 39627379, 2024). "CD36 expression in both immune and non-immune cells is known to be directly involved in cancer metastasis." (PMID 39062552, 2024). "Therefore, we demonstrate that CD36 is crucial to the development of NSCLC and that pitavastatin-mediated regulation of cancer processes depends on CD36 expression, at least in part." (PMID 38319449, 2024). "CD36 was predominantly positively correlated with M2 macrophage abundance and significantly negatively correlated with memory B cells, CD8 T cells, and T helper cells among most cancers." (PMID 38742843, 2024). "Recent studies have revealed a notable disparity in the expression of CD36 between metastatic and non-metastatic cancer cells, indicating a higher level of CD36 in the former." (PMID 38276607, 2024). "Quantitative analysis of LD content in the cancer cells confirmed that the CD36 inhibitor did not impede the IC2-induced LD formation." (PMID 39725994, 2024). "Accordingly, a relative increase of certain markers can be detected in the profile of cancer cell-derived EVs compared with normal primary astrocyte-EVs: CD44 and CD90 were elevated in LN18-EVs; CD36, CD54, CSPG4, and GD2 in LN229-EVs; CD13, CD49e, CD49f, and CD90 in NCH82-EVs." (PMID 37803478, 2023). "Altogether, considering the limited impact on normal hematopoiesis, therapeutic approaches to target CD36 in cancer are unlikely to result in toxicity to normal blood cells." (PMID 37226083, 2023). "The colorectal cancer cells also use FABP4 and FABP5, rather than CD36, to scavenge extracellular FFAs and intracellular lipids, in contrast to other cancers, such as melanoma or ovarian and prostate carcinomas." (PMID 37760840, 2023). "Moreover, CD36+ CAFs potentiated the capacity of MDSCs to enhance the immunosuppressive TME and cancer stemness." (PMID 36878933, 2023). "Therefore, further research and understanding are needed on the regulatory mechanism involving post-translational modifications of CD36 in controlling cell–cell communication within the TME since CD36 is a potential biomarker and therapeutic target for cancer." (PMID 38060103, 2023). "Lack of CD36 in the prostate tissue of mice can attenuate cancer uptake of FA organisms and reduce tumorigenesis." (PMID 35743814, 2022).
cancer (continued). "Different membrane-associated proteins are involved in the uptake of exogenous FAs by cancer cells from their environment, such as FA translocase (FAT or CD36), and FA transport protein (FATP) or in the intracellular transport of FAs, such as plasma membrane FA-binding protein (FABP)." (PMID 35945203, 2022). "CD36 transports FAs into cells and plays essential roles in cell growth, metastasis, angiogenesis, immune response, adhesion, and epithelial-mesenchymal transition (EMT) in cancers." (PMID 37305350, 2022). "In contrast, in studies showing a negative relationship, exogenous FAs were not as abundantly supplied, and cancer cells downregulated CD36 expression." (PMID 35448537, 2022). "A possible role of the PHB1/ANX2/CD36/CAV1 interactome in cancer progression remains to be determined and put into the context of what is known about other proteins, such as FATP1, which also regulate FA transport in cancer cells." (PMID 35991116, 2022). "CD36 expression correlates with high EMT and poor prognosis in patients with cancer." (PMID 35406772, 2022). "More specifically, these studies show that CD36 can promote the activation of the MAPK signaling pathway, upregulate protein expression of Bcl2 and cyclin D1 and engage with the TGF-β signaling for epithelial to mesenchymal transition (EMT) by cancer cells." (PMID 34215227, 2021). "We showed that CD36-mediated release of LCFA from WAT predetermined the reliance of cancer cells for β-oxidation as opposed to glycolysis and their increased chemoresistance." (PMID 34314388, 2021). "CD36 expression was negatively correlated with TMB and TNB in most cancer types." (PMID 34234847, 2021). "Expressions of both CD36 and the final actor of FA accumulation as neutral lipids, diacylglycerol acyltransferase (DGAT1), respectively, are regulated by TGF-β2 produced by acidosis-adapted cancer cells." (PMID 34888248, 2021). "Regarding CD36, we have demonstrated that its expression increases under oxLDL exposure, which is not demonstrated elsewhere in cancer." (PMID 34063116, 2021). "The approximately 50 kDa band, predominant in some of the cancer cell lines, is likely to be nonglycosylated CD36, as confirmed by PNGase F treatment." (PMID 34314388, 2021). "Current understanding of the regulation of CD36 expression is rather limited, and how CD36 expression is regulated in cancer, and in particular in CRC, is not known." (PMID 32850342, 2020). "Expressions of both CD36 and DGAT1, the main entry path for FA in the cytosol and the final actor of their accumulation as neutral lipids, respectively, are regulated by TGF-β2 produced by acidosis-adapted cancer cells." (PMID 31974393, 2020). "Furthermore, CD36 methylation showed a negative correlation with its mRNA levels across various cancers." (PMID 41550652, 2025). "Furthermore, CD36 was found to be upregulated during matrix detachment in a p38‐ and AMP‐activated protein kinase‐dependent manner, promoting the uptake of monounsaturated fatty acids and contributing to the metastatic potential of cancer cells." (PMID 40552664, 2025). "Periostin (POSTN) produced by cancer cells induced secretion of the chemokine CC motif chemokine ligand 2 (CCL2) by endothelial progenitor cells (EPCs), which in turn promoted a metastatic phenotype in HCC cells by increasing CD36 expression through the CCR2/STAT3 signaling pathway." (PMID 39624081, 2024). "Activated lipolysis increases caveolar endocytosis, CD36 deacylation, and CD36 dissociation from the interacting partners (prohibitin-1 and annexin 2), which contributes to the CD36-caveolar structure in the promotion of FFA mobilization from adipocytes into cancer cells." (PMID 39125923, 2024).
cancer (continued). "However, in the cancer microenvironment, a high level of TSP-2 produced by cancer-associated fibroblasts is activated via the TGF-β1/Smad2/3 pathway, binds to integrin αvβ3/CD36 and activates the MAPK pathway in cancer cells to promote tumor growth and adhesion." (PMID 38516004, 2024). "While the CD36 amyloid interaction was not evaluated in the context of cancer, it is tempting to speculate its involvement in the invasiveness of CD36+ cancer cells." (PMID 36980201, 2023). "Consequently, targeting lipid metabolism in Treg cells, such as CD36 and SREBP, may be a promising way to enhance the efficacy of cancer immunotherapy, worthy of further study." (PMID 37700339, 2023). "Moreover, adipocyte-co-cultured cancer cells displayed an increased expression level of stem cell markers (CD44, OCT4, and SOX2) which could also be further promoted via CD36 overexpression." (PMID 37371076, 2023). "Although dramatic decreases in the cancer cell metabolism gene signature ensue with combined BRAF/MEK inhibition, indicative of an overall low metabolic activity in MRD, this metabolic signature was decreased to a significantly lesser extent in the CD36+ cells, compared with the CD36– subpopulation." (PMID 37616051, 2023). "The evidence for a key metabolic role of CD36 in TAM-mediated metastasis is strong, therefore targeting the related metabolites and FAs involved in the metabolism may provide an emerging approach for cancer treatment and manipulation of TAMs." (PMID 36428985, 2022). "Additionally, the transfer of BODIPY-C16 from cancer cells to MAMs was markedly decreased when CD36 was absent in vivo." (PMID 36184646, 2022). "Furthermore, CD36 is relevant in the communication between cancer and non-cancerous cells within tumors." (PMID 36568966, 2022). "Therefore, transport proteins such as fatty acid translocase (FAT/CD36) and fatty acid-binding protein (FATP) in the FA uptake pathway may become potential targets for cancer treatment." (PMID 34803512, 2021). "This study adds to this interest by identifying a key role for CD36 in the lateral interactions with integrin-α3 to promote adhesion to the ECM (particularly laminin) to facilitate VM formation, an emerging process that contributes significantly to the progression of cancer." (PMID 34215227, 2021). "CD36 in cancer cells is not required for LCFA uptake from adipocytes." (PMID 34314388, 2021). "Therefore, inhibition of exogeneous fatty acid uptake by targeting CD36 may synergize with inhibition of desaturation by targeting SCD (e.g., via small molecules CAY-10566 and TOFA39,40) in killing hypoxic cancer cells." (PMID 32103057, 2020). "Elevated CD36 levels and the consequent elevated FFAs uptake may activate the Wnt and TGF-β signaling pathways, thereby inducing epithelial-mesenchymal transition (EMT), which is involved in cancer cell metastasis." (PMID 33364199, 2020). "Therefore, CD36, in particular dysmetabolic conditions, by suppressing AMPK activation, may enhance DNL and thereby promote cancer cell proliferation." (PMID 29167646, 2017). "In this study, we aimed to elucidate whether enhanced CD36 in mesenchymal HER2 + cancer stem cells (CSCs) is directly involved in anti-HER2 treatment refractoriness in HER2 + BC and to design future metabolism-based approaches targeting both FA reprogramming and the “root” of cancer." (PMID 39833955, 2025). "Importantly, CD36 KO did not promote peripheral autoimmunity, demonstrating that this metabolic configuration involving lipid uptake and metabolism is unique to intratumoral Tregs, highlighting the potential for targeting lipid metabolism for cancer therapy." (PMID 34983949, 2022). "In addition, inhibition of FASN (fatty acid synthase) can increase the expression of CD36 in cells, thereby increasing the proliferation of CRC cells, suggesting that the combination of inhibition of CD36 and increase of FASN expression can further increase the anti-cancer effect." (PMID 37305350, 2022).
cancer (continued). "Finally, we identified CD36 as a main entry path for exogenous FA, since the use of specific blocking antibodies (JC63.1 and FA6-152) prevented LD formation as well as the uptake of a fluorescent palmitate analog (BODIPY-conjugated C16) in acidosis-adapted cancer cells." (PMID 31974393, 2020). "Therefore, CD36 levels in cancer cells may not be primarily regulated via FA-induced degradation." (PMID 37371076, 2023). "While no change in total CD36 protein expression could be detected by immunoblotting, using a method based on surface protein biotinylation, we found an increase in the expression of CD36 at the plasma membrane in pH 6.5-adapted cancer cells as well as in native cancer cells exposed to TGF-β2." (PMID 31974393, 2020). "The fact that the expression of CPT1α (but not CD36) is upregulated by FH535 and Y3 indicates that endogenous (but not exogenous) LCFA β-oxidation (but not LCFA transport into mitochondria) is one of the main metabolic pathways altered by these sulfonamides in HCC cancer cells." (PMID 32821346, 2020).
infection (154 papers, 2006 to 2026). The state of being infected such as from the introduction of a foreign agent such as serum, vaccine, antigenic substance or organism. "Cd36−/− susceptibility to T. gondii infections was suggested to correlate with a breakdown in tissue homeostasis following infection." (PMID 39302131, 2024). "Increased expression of the FA transporter CD36 is also observed in primary endothelial cell lines after infection by pathogenic leptospires, L. interrogans." (PMID 37868347, 2023). "Sf9 cells were infected with recombinant baculovirus encoding human full-length SR-B1 or human full-length CD36 at a multiplicity of infection (MOI) of 5 to induce robust protein expression." (PMID 37625590, 2023). "Previous research showed that CD36 acts as a receptor during other infections, such as those associated with P. falciparum." (PMID 35964959, 2022). "Here, we discuss why the interaction between PfIEs and CD36 is optimal to maintain a finely regulated equilibrium that allows the parasite to multiply and spread while causing minimal harm to the host in most infections." (PMID 36557610, 2022). "Beige mRNA levels were quantified by qPCR in WT and CD36-deficient macrophages after infection with L. amazonensis amastigotes." (PMID 27280707, 2016). "Using this condition, WT cells had enlarged PVs by 3 h post infection, while the PVs in the CD36-deficient macrophages remained small, suggesting that CD36 is directly involved in the expansion and maintenance of L. amazonensis PVs." (PMID 27280707, 2016). "Next, to investigate the role of CD36 scavenger receptors in phagocytosis, the number of parasites associated with hemocytes was scored 1 h post-infection." (PMID 27280707, 2016). "Our data show that the outcome of wild type (C57BL/6J) and SR-A/CD36 deficient mice (S/C-KO) depends on the site of infection, with mirrored results after intra-nasal or intra-peritoneal infection." (PMID 24498223, 2014). "The aim of this study was to revisit the resistance of mice to S. aureus infection, evaluating the impact of the route of infection and the role of scavenger receptors SR-A and CD36 in the resistance or susceptibility." (PMID 24498223, 2014). "Consistent with results of in vivo studies, cell culture infection experiments demonstrated that CD36 deficiency limits intracellular replication of mycobacteria in macrophages." (PMID 20950462, 2010). "CD36 was up-regulated by M. tuberculosis H37Ra infection in macrophages and suppressed in exosomes from H37Ra-infected macrophages indicating that CD36 could be a potential biomarker associated with TB infection." (PMID 38881887, 2024). "Considering this, inhibition of free PA uptake by genetic deletion of Cd36 leading to a dampened inflammatory response may contribute to enhanced susceptibility to infection and decreased TLR2-mediated inflammation." (PMID 37197687, 2023). "It remains to be determined whether genetic variations in MARCO and CD36 alter the expression of these receptors and whether genetic polymorphisms impact the severity of infection and the persistence of Mtb over a longer time period." (PMID 28693442, 2017). "By comparing the transcriptomic profiles of infected cells, bystander cells, and unexposed cells, we identified precise modulation of several key pathways: first, the "Fabp4/Cd36 lipid metabolism pathway" is activated during early infection." (PMID 41827050, 2026). "This review will comprehensively investigate CD36’s functions in lipid uptake and processing, inflammatory response, immune response and therapeutic targets and biomarkers in the infection process of M. tuberculosis." (PMID 38881887, 2024). "Changes in the expression of the LOX, ABCA1 and CD36 genes in the CETP mice indicate a possible association between lipid metabolism and the response to infection." (PMID 38966642, 2024).